BCL2 (BCL2 apoptosis regulator)
Diseases named in the same sentence as BCL2 in open-access papers (continued):
Sharing a sentence is not in itself a finding about the gene and the disease.
breast carcinoma (continued). "Similarly, silibinin is a flavonolignan, extracted from milk thistle (Silybum marianum), and has been reported to provoke autophagic cell death in breast cancer cells by downregulating the Bcl-2 expression and upregulation of Atg12-Atg5 formation and enhancing beclin-1 expression." (PMID 29681985, 2018). "Similarly, in paclitaxel-resistant breast cancer, it was demonstrated that miR-451 may also inhibit BCL2." (PMID 29164055, 2017). "Furthermore, the activation of the AMPK-mediated apoptotic signaling pathway may play an important role in apoptosis by modulating the Bcl-2/Bax ratio, as also reported for breast cancer cells." (PMID 29234282, 2017). "In previous study, Bcl2 could inhibit Beclin1 dependent autophagy in human breast carcinoma cells." (PMID 28106136, 2017). "To date, several meta-analyses have demonstrated that various biomarkers may be associated with the survival of patients with breast cancer, including p27, vascular endothelial growth factor (VEGF), Cyclooxygenase (COX-2), B cell lymphoma 2 protein (BCL-2), and cyclin D1." (PMID 28410191, 2017). "MiR- 24-2 expression may confer cisplatin sensitivity in breast cancer by targeting Bcl-2." (PMID 27083050, 2016). "Taken together these data suggest that MYB regulation of BCL2 underlies the heightened sensitivity of ER+ve compared to ER−ve breast cancer cells to CDK9 inhibition, and that these compounds represent a potential therapeutic for ER+ve breast cancers and possibly other MYB-dependent cancers." (PMID 26812885, 2016). "Thus, the functional release of Bcl-2 from Beclin-1 interaction may represent the molecular bridge connecting autophagy to an irreversible G1 arrest, thus determining breast cancer cell fate decision." (PMID 27462784, 2016). "Previously, our team also found that miR-34a inhibited the proliferation and migration of breast cancer cells by downregulating Bcl-2 and SIRT118, and we have developed the T-VISA-miR-34a which may provide a useful, specific, and safe targeted therapeutic strategy for breast cancer." (PMID 26902416, 2016). "Similarly, it was shown that both DHA and EPA could reduce expression of the anti-apoptotic proteins Bcl-2 and Bcl-XL in cultured breast cancer MDA MB-231 cells." (PMID 26295255, 2015). "In order to elucidate the independent clinicopathological role of Bcl-2 in breast cancer, Bcl-2 expression was assessed immunohistochemically and compared with other clinicopathological factors and with clinical outcome in 1081 breast cancer cases with a long follow-up period." (PMID 26472348, 2015). "However, bcl-2 gene expression decreased in treated breast cancer cells." (PMID 25548920, 2014). "Furthermore, the results of Hoechst staining and FCM assays demonstrated that niclosamide induced apoptotic death in breast cancer cells in a concentration-dependent manner, which was further confirmed by the down-regulation of Bcl-2 and the up-regulation of cleaved caspase-3." (PMID 24416452, 2014). "Relatively high DFS in BCL-2-positive TN tumours obtained by us could also confirm results of earlier reports, showing that a subset of TN breast cancer patients responded to standard chemotherapy and had survival rate similar to women with other breast cancer immunophenotypes." (PMID 25005788, 2014). "In addition, β2-M siRNAs may up-regulate the Bcl-2 mRNA expression via increasing HER-2 expression in breast cancer cells with ER−, PR− and HER-2− status." (PMID 25292288, 2014). "Thus, the anti-apoptotic protein Bcl-2 is expressed in 25% to 50% of breast cancer." (PMID 24124558, 2013). "Bcl2 may be both oncogenic and tumor suppressive in specific cell types or under specific conditions, and it is postulated that the tumor suppressive effect is more prominent in breast cancer." (PMID 23573235, 2013).
breast carcinoma (continued). "Furthermore, a combined mitotic/BCL2 or Ki67/BCL2 index reflects true biological variation in breast cancer and may provide more relevant prognostic information." (PMID 22424533, 2012). "Moreover, combining GSIXII treatment with ABT-737, a BH3-mimetic inhibitor of additional antiapoptotic proteins, such as Bcl-2 and Bcl-xL, leads to both a synergistic apoptotic response in breast cancer cells and to an inhibitory effect on mammosphere formation." (PMID 22703841, 2012). "Interestingly, PI3K as well as NF-κB and Bcl2 were reported to be a molecular target of plumbagin in human breast cancer cells–plumbagin dramatically decreased the level of the PI3K subunit p85, thereby inhibiting the downstream Akt/mTor pathway leading to growth arrest and cell death." (PMID 23028742, 2012). "In addition, tumour grade, triple-negative and basal-like breast cancers, ER, Ki-67 and bcl-2, were associated with breast cancer-specific survival in our study." (PMID 21835023, 2011). "Furthermore, it has been shown to protect breast cancer cells from mitochondrial-mediated apoptosis, through modulation of Bcl-2 family member proteins, including up-regulation of anti-apoptotic Bcl-2 and down-regulation of pro-apoptotic members Bad, Bak and PUMA." (PMID 24212627, 2011). "Hence, analyses of the protein sequence for HLA-binding motifs and subsequent testing of blood of tumor patients revealed spontaneous T-cell reactivity against Bcl-2 in patients suffering from unrelated tumor types, i.e., melanoma, pancreatic and breast cancer, as well as AML and B-CLL." (PMID 21304176, 2010). "Through the rank correlation analysis we found that there was a negative correlation between the BCL-2 expression and the chemosensitivity in breast cancer, indicated that BCL-2 maybe made the breast cancer cells resistant to chemotherapy drugs through its anti-apoptotic function." (PMID 20691103, 2010). "The mechanisms through which BCL2 might exert its protective effect in breast cancer are unclear." (PMID 18510726, 2008). "Furthermore, in 2000 this group showed that Bcl-2 immunostaining could potentially replace TUNEL as its prognostic value is well-established in breast cancer." (PMID 17325701, 2007). "Finally, most human breast cancers originate in epithelial cells that express Bcl-2 or Bcl-XL." (PMID 16928273, 2006). "Bcl2 is an anti-apoptotic protein overexpressed in about 60 to 80% of breast cancers, and several studies suggest that the low apoptotic response caused by that overexpression allows the accumulation of genetic alterations that might be important in breast cancer metastatic potential." (PMID 16168125, 2005). "The differential effects of Bcl-2 and Bcl-xL on drug sensitivity might be unique to breast cancer." (PMID 16280040, 2005). "Indeed, in breast cancer and thyroid carcinoma, Bcl-2 positivity also showed a favourable outcome." (PMID 14710230, 2004).
breast carcinoma (continued). "Alterations in the BCL-2 protein family, with overexpression of anti-apoptotic members (e.g., BCL-2, BCL-xL) and downregulation of pro-apoptotic counterparts (e.g., BAX, PUMA), contribute to apoptosis evasion in breast cancer." (PMID 41531509, 2026). "Another study in breast cancer showed that PARK2 promotes mitochondrial pathway of apoptosis and antimicrotubule drugs chemosensitivity via degradation of phospho‐BCL‐2." (PMID 40638546, 2025). "Emodin-loaded polymer lipid hybrid nanoparticles (E-PLNs) exhibited superior anti-cancer efficacy against breast cancer (MCF-7) cells by enhancing uptake, promoting early apoptosis via Bax/Bcl-2 pathway, and inhibiting tumor growth by over 60% in mice." (PMID 40490812, 2025). "We examined the clinical correlation of four key genes (PSMB8, BCL2, BMP5, and PSME2) with breast cancer prognosis." (PMID 41403941, 2025). "We used the IMMUcan database to analyze single-cell RNA data and examine the expression of PSMB8, BCL2, and PSME2 in the breast cancer immune microenvironment." (PMID 41403941, 2025). "The TCGA-BRCA breast cancer dataset exhibits separate Kaplan–Meier survival curves (KM) for four notable genes (PSMB8, BCL2, BMP5, and PSME2)." (PMID 41403941, 2025). "In a breast cancer study, NRP1 overexpression was found to interfere with the m6A-dependent downregulation of the Bcl-2 mRNA via WTAP and improve DNA repair ability, which in turn protects breast cancer cells from apoptosis and promotes radioresistance." (PMID 39972266, 2025). "Previous studies have shown that juglone treatment reduces BCL-2 protein levels while increasing active caspase-3 levels in ovarian cancer SKOV3 and human breast cancer MCF-7 cells." (PMID 39948289, 2025). "In MCF-7, MCF-10A, HMEC, and MDA-MB 231 breast cancer cells, HSP (20–200μM) was found to increase ROS production, cyto-C release, Bax/Bcl-2 ratio, PARP cleavage, caspase-9, -3, -7, JNK, and sk1 activation, in addition to the activation of the ASK1/JNK pathway." (PMID 40427522, 2025). "Studies in MCF-7 breast cancer cells further support this mechanism, showing activation of mitochondrial apoptosis through the ROS/JNK/ATF-2/Bcl-2 axis." (PMID 41303402, 2025). "Consistently, treatment of MDA-MB-231 breast cancer cells with 3-HBI increased apoptotic cell death, accompanied by decreased Bcl-2 and significantly increased Bax expression." (PMID 41009343, 2025). "To elucidate the mechanisms underlying the suppression of cell proliferation and induction of apoptosis in breast cancer cells by APS, DDP, and the combination of APS and DDP, we analyzed apoptosis-related proteins (Cle-PARP, Cle-Caspase3, Bcl2, and Bcl-xL)." (PMID 40109863, 2025). "Mechanistic investigations suggest that melittin suppresses breast cancer progression by inhibiting growth factor receptor activation (e.g., HER2) and inducing apoptosis through caspase activation and modulation of the Bax/Bcl-2 pathways." (PMID 40871040, 2025). "This is notably the case of navitoclax (an inhibitor of BCL-2, BCL-xL, and BCL-W), which had a high synergy rate with paclitaxel in some subtypes of breast cancer." (PMID 39170706, 2024). "In breast cancer, the METTL3-METTL14 complex upregulates the expression of genes like Bcl-2 and CXCR4 through m6A-dependent mechanisms, thereby fostering breast cancer growth and metastasis." (PMID 38965238, 2024).
breast carcinoma (continued). "IATL increases the Bax/Bcl-2 ratio, mediates the mitochondrial pathway, and suppresses the MAPK/NF-κB signaling pathway to induce apoptosis in breast cancer cells." (PMID 39382942, 2024). "Serological markers are of significant importance in both the diagnosis and prognosis of breast cancer, with Ki67, CA 15-3, BAX, and Bcl-2 being notably characteristic in luminal subtype tumors." (PMID 38256428, 2024). "In breast cancer, ONECUT2 inhibits CASP3 and activates BCL2, which together support survival of these tumor cells." (PMID 38474011, 2024). "The capacity of SHBG to suppress bcl-2 expression counteracts the typical gene amplification caused by estradiol, which may be one of the mechanisms of SHBG binding to its membrane receptor and then combining with estrogen to induce recovery of apoptosis in breast cancer cells." (PMID 38465341, 2024). "Specifically, in breast cancer, ZKSCAN3 expression exhibits a positive correlation with CCND1 and BCL2 expression, while it negatively correlates with the expression of Bcl2 Associated X Protein (Bax)." (PMID 39519085, 2024). "These conclusions also translate into the results of our study to determine the level of Bcl-2 in MCF-7 and MDA-MB-231 breast cancer cells." (PMID 39063006, 2024). "stems against SW480 colon and MCF7 breast cancer cells, evidenced by reduced COX-2 expression levels and an elevated Bax/Bcl2 ratio indicative of apoptosis." (PMID 39495776, 2024). "After targeting our 3D breast cancer model with OLE-mALG (200 μg/mL, 7 h), level of Bax apoptotic protein increased, while the level of Bcl-2 decreased." (PMID 38722566, 2024). "Three essential core genes—EGFR, BCL2, and MAPK3—in the PPI network of breast cancer-related targets of SP were among the top ten genes." (PMID 39057437, 2024). "Consistently, in the stromal adipocytes of breast cancer, PGE2 has upregulated aromatase production to stimulate tumor cell proliferation and promoted cell survival by inducing Bcl-2, the anti-apoptotic protein, via Ras-MAPK signaling." (PMID 38704736, 2024). "BCL-2 has been proposed as an additional prognostic marker that can be used in conjunction with ER, PR, HER2, and Ki-67 to predict the Oncotype DX breast cancer recurrence score." (PMID 36765765, 2023). "Therefore, Bcl-2 may be a potential anti-angiogenic therapeutic target for breast cancer therapy." (PMID 37237269, 2023). "miR-34a plays an inhibitory role by targeting Bcl-2 and SIRT1 and down-regulating their expression in breast cancer." (PMID 37333450, 2023). "In HER2‐positive breast cancer, lncRNA‐SNHG14 induces exosome‐mediated trastuzumab resistance by targeting the apoptosis regulator Bcl‐2/BAX signaling." (PMID 37229486, 2023). "The present study demonstrated that the expression of the proapoptotic protein, Bax, increased but that the expression of the antiapoptotic protein, Bcl‐2, decreased when ZNF‐148 was knocked down in breast cancer cells." (PMID 37909239, 2023). "BCL-2 was also the target of METTL3, which regulated breast cancer’s proliferation and apoptosis in a m6A modification pathway." (PMID 36970605, 2023). "The BAX/BCL2 ratio in MCF-7 cells was 1.2 after 24 h of cultivation with CIMVs-TRAIL, which also confirms the induction of apoptosis in breast cancer cells." (PMID 36661524, 2023).
breast carcinoma (continued). "In particular, quercetin induced intrinsic apoptotic mechanism via bax increase, bcl-2 decrease, MMP decrease, AIF release and caspase-6, -9 activation in MCF-7 breast cancer cells." (PMID 36675194, 2023). "Recent studies have reported that Ferula assa-foetida L. essential oil nano-emulsion can lead to apoptosis by decreasing BCL-2 and increasing BAX expression in MCF7 breast cancer cells." (PMID 38138502, 2023). "LncRNA NONHSAT141924 was found to promote paclitaxel resistance by inhibiting the p-CREB/Bcl-2 apoptosis pathway, and overexpression of lncRNA NONHSAT141924 increases Bcl-2 and p-CREB protein levels in breast cancer." (PMID 37569629, 2023). "Our findings demonstrated that CYD0281 is a potential Bcl-2 BH4 antagonist as a useful research tool inhibitor and a promising therapeutic agent for angiogenesis and breast cancer." (PMID 37237269, 2023). "In breast cancer cells, GPR176 silencing was shown to ameliorate proliferation and induce apoptosis by either inactivating PTEN/PI3K/Akt/mTOR or decreasing Bcl-2/Bax." (PMID 37079213, 2023). "In their study, compared to HER2-zero breast cancer, the expression of luminal-related genes such as BCL2 and FOXA1 was upregulated in HER2-low breast cancer." (PMID 37770874, 2023). "Compared to MENs+DOX without MF, MENs+DOX with 45 min MF significantly decreased the expression level of BCL2 and enhanced the expression level of BAX and Caspase 3 genes in 4T1 breast cancer cells." (PMID 37845238, 2023). "A genetic engineering study of the NK-92MI using lentiviral transduction to express BCL-2 siRNA (siBCL-2), which is enriched in NEVs and successfully enhanced tumor-killing ability by inhibiting overexpression of BCL-2 in breast cancer." (PMID 37064251, 2023). "Interestingly, high Bcl-2 protein expression has been associated with an early grade, slow-proliferating ER+ profile and favorable outcomes in breast cancer, independent of many pathophysiological characteristics such as lymph node status, tumor size, and grade." (PMID 37370761, 2023). "Here, we used the same series of breast cancer cases, from a multi-racial population with defined clinical characteristics and survival data, to measure the protein expression of SGK1 and Bcl-2." (PMID 37370761, 2023). "In breast cancer cells overexpressing GRP78, the expression level of anti-apoptotic protein Bcl-2 was increased, while the expression of pro-apoptotic proteins Bax and Bim was decreased." (PMID 38105649, 2023). "Most primary and metastatic ER+ breast cancer cells overexpress BCL-2, which makes targeting BCL-2 possible to treat this type of breast cancer." (PMID 37352173, 2023). "BCL2 and TGF expression in breast cancer has been documented to be connected with a better prognosis in patients treated with hormones orchemotherapy, among several protein expression pathways in cancer." (PMID 37720282, 2023). "At least three genes from this list were involved in the formation of carcinomas, including breast carcinoma (CASP8, HSPA4, BCL2L11), prostate carcinoma (BCL2, CASP8, BCL2L11, ATM), and chronic lymphocytic leukemia (BCL2, CASP8, FAS, BCL2L11, BAK1)." (PMID 37298337, 2023). "Low expression levels of DEDD served as an indicator of higher sensitivity to venetoclax in breast cancers, as DEDD downregulation rendered BCL-2 unstable and accelerated its degradation." (PMID 37894324, 2023). "Bcl-2 and bcl-xL downregulation was observed in MDA-MB-231 breast cancer cells together to endogenous copper ions’ mobilization and ROS generation." (PMID 36675194, 2023). "Bcl-2 and Bcl-xL also regulate mitochondrial dynamics and support metabolic robustness by elevating NAD(P)H and ATP in breast cancer cells." (PMID 37046596, 2023).